TUT4 (terminal uridylyl transferase 4)
Description:
Uridylyltransferase that mediates the terminal uridylation of mRNAs with short (less than 25 nucleotides) poly(A) tails, hence facilitating global mRNA decay. Essential for both oocyte maturation and fertility. Through 3' terminal uridylation of mRNA, sculpts, with TUT7, the maternal transcriptome by eliminating transcripts during oocyte growth (By similarity). Involved in microRNA (miRNA)-induced gene silencing through uridylation of deadenylated miRNA targets. Also functions as an integral regulator of microRNA biogenesis using 3 different uridylation mechanisms. Acts as a suppressor of miRNA biogenesis by mediating the terminal uridylation of some miRNA precursors, including that of let-7 (pre-let-7), miR107, miR-143 and miR-200c. Uridylated miRNAs are not processed by Dicer and undergo degradation. Degradation of pre-let-7 contributes to the maintenance of embryonic stem (ES) cell pluripotency (By similarity). Also catalyzes the 3' uridylation of miR-26A, a miRNA that targets IL6 transcript. This abrogates the silencing of IL6 transcript, hence promoting cytokine expression. In the absence of LIN28A, TUT7 and TUT4 monouridylate group II pre-miRNAs, which includes most of pre-let7 members, that shapes an optimal 3' end overhang for efficient processing. Adds oligo-U tails to truncated pre-miRNAS with a 5' overhang which may promote rapid degradation of non-functional pre-miRNA species. May also suppress Toll-like receptor-induced NF-kappa-B activation via binding to T2BP. Does not play a role in replication-dependent histone mRNA degradation. Due to functional redundancy between TUT4 and TUT7, the identification of the specific role of each of these proteins is difficult (By similarity). TUT4 and TUT7 restrict retrotransposition of long interspersed element-1 (LINE-1) in cooperation with MOV10 counteracting the RNA chaperonne activity of L1RE1. TUT7 uridylates LINE-1 mRNAs in the cytoplasm which inhibits initiation of reverse transcription once in the nucleus, whereas uridylation by TUT4 destabilizes mRNAs in cytoplasmic ribonucleoprotein granules.
Synonyms: KIAA0191; ZCCHC11; PAPD3; TENT3A
Tractability: PROTAC: ubiquitination databases record sites on it.
Gene: Protein-coding gene on chromosome 1 (52,408,282 to 52,553,487, reverse strand). Ensembl gene ENSG00000134744.
Subcellular location: Nucleus; Cytoplasm; Cytoplasm, Cytoplasmic ribonucleoprotein granule
Subcellular location (Human Protein Atlas): Cytosol; Nucleoli
Pathways (Reactome):
Developmental Biology: Z-decay: degradation of maternal mRNAs by zygotically expressed factors; Zygotic genome activation (ZGA)
Metabolism of RNA: Deadenylation of mRNA
Gene Ontology:
Molecular function: protein binding; RNA binding; RNA uridylyltransferase activity; miRNA binding; nucleic acid binding; nucleotidyltransferase activity; zinc ion binding
Biological process: histone mRNA catabolic process; miRNA catabolic process; miRNA metabolic process; pre-miRNA processing; RNA 3'-end processing; stem cell population maintenance; transposable element silencing by mRNA destabilization; oocyte maturation; polyuridylation-dependent mRNA catabolic process
Cellular component: cytoplasm; cytoplasmic ribonucleoprotein granule; cytosol; extracellular exosome; extracellular region; nucleus
Genetic constraint (gnomAD): Loss-of-function variants: 27 observed, 154.45 expected, observed/expected ratio (o/e) 0.17, 90% interval 0.13 to 0.24. The upper end of that interval is the gene's LOEUF score, 0.24, which puts it in group 1 of 6, group 1 being the genes least tolerant of losing a copy. Missense variants: 1,375 observed, 1,859.1 expected, observed/expected ratio (o/e) 0.74, 90% interval 0.71 to 0.77. Synonymous variants: 571 observed, 644.43 expected, observed/expected ratio (o/e) 0.89, 90% interval 0.83 to 0.95.
Homologues: Orthologues: chimpanzee TUT4 (98% identical), macaque TUT4 (97% identical), pig TUT4 (91% identical), dog TUT4 (91% identical), rabbit TUT4 (90% identical), rat Tut4 (88% identical), mouse Tut4 (88% identical), guinea pig TUT4 (85% identical), tropical clawed frog tut4 (53% identical), Caenorhabditis elegans cid-1 (18% identical), Caenorhabditis elegans gld-2 (10% identical), Caenorhabditis elegans pup-2 (8% identical), and 5 more. Paralogues in human: TUT7 (36% identical), TUT1 (9% identical), TENT2 (8% identical), MTPAP (6% identical).
Diseases named in the same sentence as TUT4 in open-access papers:
TUT4 is named in the same sentence as 16 diseases in open-access papers, as found by Europe PMC text mining. Sharing a sentence is not in itself a finding about the gene and the disease. The quoted sentences say what the papers report.
breast carcinoma (4 papers, 2011 to 2021). "In addition to the role of uridylation in LIN28A-expressing cancers, TUT4 is implicated in both gliomas and breast cancer, independently of the LIN28/let-7 pathway." (PMID 30057901, 2018). "When taken together, these results suggest that TUT4 overexpression in certain contexts may contribute to poor clinical prognosis in breast cancer." (PMID 30057901, 2018). "In breast cancer, Hallett and Hassell defined a dual gene classifier to predict breast cancer survival using E2F1 and TUT4 (i.e., KIAA0191; Hallett and Hassell, 2011)." (PMID 30057901, 2018).
cervical cancer (1 paper, 2022). A primary or metastatic malignant neoplasm involving the cervix. "Furthermore, mono-adenylation at 19 predicted targets of TUT4/7, which are all derived from 5p pre-miRNA arms, simultaneously increases upon TUT4/7 depletion and loss of mono-uridylation in the cervical cancer cell line HeLa." (PMID 34949722, 2022).
embryonal carcinoma (1 paper, 2018). A non-seminomatous malignant germ cell tumor characterized by the presence of large germ cells with abundant cytoplasm resembling epithelial cells, geographic necrosis, high mitotic activity, and pseudoglandular and pseudopapillary structures formation. "They reported that double knockdown of both TUT4 and TUT7 increased let-7 more than TUT4 knockdown alone in mouse embryonic stem (ES) and P19 embryonal carcinoma cells that express Lin28A." (PMID 30057901, 2018).
esophageal squamous cell carcinoma (1 paper, 2022). Esophageal squamous cell carcinoma (ESCC) is a type of esophageal carcinoma (EC) that can affect any part of the esophagus, but is usually located in the upper or middle third. "A recently identified substrate of TUT4/7, known as miRNA-27a, downregulates the expression of HSP90 in esophageal squamous cell carcinoma." (PMID 36497000, 2022).
glioma (1 paper, 2018). A benign or malignant brain and spinal cord tumor that arises from glial cells (astrocytes, oligodendrocytes, ependymal cells). "Proteomic studies have also revealed that overexpression of TUT4 is common in high grade gliomas in comparison to low grade." (PMID 30057901, 2018).
male infertility (1 paper, 2024). The inability of the male to effect fertilization of an ovum after a specified period of unprotected intercourse. "Deletion of both TUT4 and TUT7 in pre-meiotic germ cells by using Stra8-Cre mice leads to spermatogenic arrest in the late pachytene stage, accompanied by cell apoptosis, ultimately resulting in spermatogenic failure and male infertility." (PMID 39310107, 2024).
ovarian carcinoma (1 paper, 2022). A malignant neoplasm originating from the surface ovarian epithelium. "TUT4/7 loss has a greater impact on the cancer cell properties of the ovarian cancer cell line IGROV1 than the prostate cancer cell line DU145." (PMID 34949722, 2022). "Here we provide a global view of changes in miRNA variant populations in the TUT4/7 double mutants of the prostate cancer cell line DU145 and the ovarian cancer cell line IGROV1." (PMID 34949722, 2022). "We find that TUT4/7 catalyze most of the miRNA uridylation in the prostate cancer cell line DU145 and the ovarian cancer cell line IGROV1." (PMID 34949722, 2022). "This study focuses on the prostate cancer cell line DU145 and the ovarian cancer cell line IGROV1, as both cell lines have been previously reported to show reduced cell proliferation and tumor growth in xenograft models upon TUT4 transcript depletion via siRNAs or shRNAs." (PMID 34949722, 2022). "Contrary to a previous study in cervical-derived HeLa cells, which concluded that the functional activity of both TUT4 and TUT7 is vital for cell viability, our data show that TUT4 and TUT7 are not required for viability in the prostate cancer cell line DU145 and the ovarian cancer cell line IGROV1." (PMID 34949722, 2022).
prostate carcinoma (1 paper, 2022). A carcinoma that arises from epithelial cells of the prostate gland. "A PCA on all genotypes of the prostate cancer DU145-derived cell lines shows that PC1 versus PC2 captures clonal variation, whereas PC2 versus PC3 captures the variation in the data that is associated with the presence or absence of TUT4/7." (PMID 34949722, 2022). "Therefore, the absence of TUT4/7-mediated miRNA regulation has a higher impact on the IGROV1 cell line relative to the prostate cancer cell line DU145." (PMID 34949722, 2022).
tumor (15 papers, 2011 to 2024). "This suggests that the severity of cellular phenotypes upon TUT4/7 loss may be cell-line or tumor specific." (PMID 34949722, 2022). "In addition, for the IGROV1 cell line, TUT4/7-mediated regulation may prepare the tumor for the next stage of cancer, that is, metastasis, as cell migration, “wound healing,” and “angiogenesis” related genes are deregulated upon TUT4/7 loss." (PMID 34949722, 2022). "The knockdown of TUT4 leads to decreased tumour volume in cells expressing high levels of the RNA-binding protein LIN28A, a common feature of HER2+ cancers." (PMID 36497000, 2022). "In breast cancer models, TUT4 inhibition has preventative effects on tumour formation, making it a potential chemotherapy target." (PMID 36497000, 2022). "The human terminal uridyl transferases TUT4 and TUT7 (TUT4/7) catalyze the additions of uridines at the 3′ end of RNAs, including the precursors of the tumor suppressor miRNA let-7 upon recruitment by the oncoprotein LIN28A." (PMID 34949722, 2022). "For example, the RNA binding protein and proto-oncogene LIN28A and TUT4 work together to polyuridylate pre-let-7, thereby blocking biogenesis and function of the tumor suppressor let-7 microRNA family." (PMID 30057901, 2018). "The tumour suppressor let-7 miRNAs have previously been identified as TUT4/7 substrates, and a recent study similarly identified increased abundance of these miRNAs upon TUT4/7 deletion." (PMID 36497000, 2022). "The terminal RNA uridyl transferases TUT4 and TUT7 (TUT4/7) are the enzymes responsible for catalyzing the addition of Us at the 3′ end of miRNAs such as the tumor suppressor let-7s, to regulate their expression levels." (PMID 34949722, 2022). "Tumor-suppressor let-7 pre-microRNAs (miRNAs) are regulated by terminal uridylyltransferases TUT7 and TUT4 that either promote let-7 maturation by adding a single uridine nucleotide to the pre-miRNA 3′ end or mark them for degradation by the addition of multiple uridines." (PMID 39054354, 2024). "TUT4 is a non-templated poly-uridylase that plays a key role in the biogenesis of the tumour suppressor let-7 miRNA, and that contains three CCHC zinc fingers." (PMID 25586222, 2015).
cancer (14 papers, 2015 to 2025). A tumor composed of atypical neoplastic, often pleomorphic cells that invade other tissues. "Upon TUT4/7 mutation, we observe a significant reduction in miRNA uridylation, which results in defects in cancer cell properties such as cell proliferation and migration." (PMID 34949722, 2022). "Thus, our findings provide a new avenue for the development of anticancer therapeutics as well as highlighting the importance of further investigations for the cell-type-specific roles of TUT4/7 in cancer and the underlying isomiR biology." (PMID 34949722, 2022). "Understanding of the underlying biology of such cell-type-specific deregulation will be an important aspect of targeting TUT4/7 for potential cancer therapies." (PMID 34949722, 2022). "As the TUT4/7 double mutants of DU145 and IGROV1 were viable, we examined the TUT4/7 double mutants for possible defects in cancer cell properties such as cell proliferation, wound healing, and cell migration." (PMID 34949722, 2022). "This is consistent with previous studies performed in multiple cancer cell lines, suggesting a general role of TUT4/7 in cell proliferation." (PMID 36071058, 2022). "In this study, we investigate TUT4/7-mediated RNA regulation in two cancer cell lines by establishing catalytic knockout models." (PMID 34949722, 2022). "Together, these results indicate substantial roles for TUT4/7 in cell signalling, cell adhesion, and cancer signalling." (PMID 36497000, 2022). "Expression levels of miR-200c-3p and miR-141-3p are regulated by TUT4/7 in a cancer cell-type-specific manner." (PMID 34949722, 2022). "Here, we explored the global TUT4/7-mediated RNA regulatory networks in two different cancer cell line models with distinct tissues of origin." (PMID 34949722, 2022). "In cancers such as glioblastomas overexpressing TUT4 and TUT7, pre-miR-324 is uridylated at the 3′ end, which leads to the 3′ arm-derived miR-324-3p being more abundant than the miR-342-5p derived from the 5′ arm of the same precursor hairpin." (PMID 34949722, 2022). "The structure of the LIM of TUT4, presented in this study, also provides advanced structural information for the design of therapeutic cancer drugs to target the LIM of TUT4/7 and regulate the biogenesis of the let-7 family." (PMID 31036859, 2019). "Therefore, our results suggest that TUT4/7-dependent miRNA-mediated mRNA regulation varies depending on the cancer cell line of study, which results in observed differences in defects of cancer cell properties." (PMID 34949722, 2022). "This will require further investigations as our data suggests that the severity of TUT4/7 inhibition may differ depending on the cancer cell type or the stage of cancer progression." (PMID 34949722, 2022). "These inherent differences in TUT4/7-mediated RNA regulation could also possibly depend on the cancer status and the stage of cancer progression, where TUT4/7 modulate transcriptomic changes based on the current requirements for tumorigenesis." (PMID 34949722, 2022). "Thus, the structure of the LIM of TUT4 presented in this study provides structural information for the design of anti-cancer drugs targeting the TUT4/7 activity affecting let-7 biogenesis, by blocking the interactions between TUT4/7 and Lin28." (PMID 31036859, 2019). "The miRNA set enrichment analysis for Cluster 4 and 12 show “cell growth” and “differentiation”-related terms, suggesting that these miRNAs might contribute to the slow growth phenotype in the TUT4/7 double mutants of the metastatic-site derived DU145 cancer cell line." (PMID 34949722, 2022). "In mouse embryonic stem cells (mESCs) and certain cancer cells, TUT4/ZCCHC11 or TUT7/ZCCHC6 catalyze oligo-uridylation of pre-let-7, leading to its destabilization." (PMID 40243428, 2025). "Due to its involvement in the LIN28A:let-7 axis, special attention has been brought on the efficacy of targeting TUT4 and TUT7 to negatively impact cancer proliferation and progression." (PMID 34949722, 2022).
cancer (continued). "Therefore, our results suggest that the loss of the full-length TUT4/7 have negative consequences for cancer cell properties and the severity may depend on the cancer cell line or the stage of cancer progression." (PMID 34949722, 2022). "In embryonic stem cells and cancer cells, TUT4 and TUT7 (TUT4/7) have been shown to oligo-uridylate precursors of let-7 family miRNAs in concert with the processivity factor Lin28." (PMID 25979828, 2015). "Zcchc11 (TUT4) and Zcchc6 (TUT7) modify, through 3′ uridylation, a specific microRNA group that shares a TUTase recognition sequence motif and targets proteins belonging to the Homeobox family in P19 embryonal carcinoma cells from mouse." (PMID 34178993, 2021). "TUT4 and the closely related TUT7 are non-templated poly(U) polymerases required at different stages of development, and their mis-regulation or mutation has been linked to important cancer pathologies." (PMID 34719327, 2021).
infection (2 papers, 2023 to 2024). The state of being infected such as from the introduction of a foreign agent such as serum, vaccine, antigenic substance or organism. "At late stages of infection, the population of uridylated subgenomic RNAs with tails shorter than ~22 nucleotides is reduced in the absence of TUT4/7 while the viral RNA load increases." (PMID 37085578, 2023).
TUT4 also shares sentences with these, for which no sentence is quoted: age-related macular degeneration (1 paper); esophagitis (1); Failure to thrive (1); head and neck carcinoma (1); liver cancer (1).